CAT (catalase)
Diseases named in the same sentence as CAT in open-access papers (continued):
Sharing a sentence is not in itself a finding about the gene and the disease.
tumor (continued). "Another approach involves the use of oxygen-generating or oxygen-carrying nanocarriers, such as catalase (CAT) and perfluorocarbons (PFCs), to produce or deliver oxygen directly into hypoxic regions, improving tumor oxygenation and sensitizing tumor cells to treatment." (PMID 39361163, 2024). "SOD1, CAT, GPX1, and HIF-1α were significantly increased in the lungs of tumour-bearing mice." (PMID 39506978, 2024). "This was evidenced by increased catalase activity which led to significantly less ROS-mediated, inflammatory colonic damage and tumor appearance compared to a non-catalase-producing bacterium counterpart in murine models." (PMID 39201713, 2024). "In the tumor tissues obtained from the MKN45 cell xenograft model, the tEx(D) treatment led to the most substantial reduction in the expressions of the antioxidant enzymes SOD2 and catalase (p < 0.05)." (PMID 39201449, 2024). "In order to assess the potential of D1 and D2 derivatives to induce oxidative stress in tumor cells but not in normal cells, CAT activity, GSH level, and MDA concentration were measured within this study." (PMID 38399259, 2024). "In response to oxidative stress, various antioxidant enzymes such as superoxide dismutases (SODs), catalases (CAT), peroxiredoxins (PRXs), GSH peroxidases (GPXs), and thioredoxins (TRXs) are upregulated or activated to neutralize ROS in tumor cells effectively." (PMID 39061897, 2024). "Recent research has proposed that the interplay of catalase activity, keratinocyte-induced oxidative stress by UVB, and H2O2 production, could be key in understanding tumor induction on the skin." (PMID 38672589, 2024). "Catalase (CAT) is a vital oxidoreductase in the human body, which plays a significant role in catalyzing the elimination of ROS, safeguarding cell membrane integrity, and inhibiting tumor cell growth." (PMID 37686145, 2023). "Trying to unravel and understand how the oxidative metabolism was modulated under pepper treatment in both tumor cells lines, Hep-G2 and MIA PaCa-2, this work also focused on a set of antioxidant enzymes such as catalase (CAT), superoxide dismutase (SOD), and glutathione peroxidase (GPX)." (PMID 37507999, 2023). "Perhaps the most striking result of this study was that neither the introduction of extra- or intracellular catalase activity to the tumor induced transcriptional changes that would suggest significant changes in the levels of hydrogen peroxide or oxygen." (PMID 37311396, 2023). "Despite confirming long-lived catalase presence and activity at the tumor, we did not attempt to specifically test how and if these tumor-localized catalases impact tumor hydrogen peroxide levels." (PMID 37311396, 2023). "In flank tumor models, catalase has not shown efficacy as a monotherapy, but produced cures in combination with radiation, which was attributed to hypoxia reduction." (PMID 37311396, 2023). "Among them, catalase could effectively improve the efficacy of oxygen supply and PDT treatment because of the catalytic decomposition of elevated H2O2 in the tumor environment." (PMID 37007107, 2023). "Nevertheless, the combined effects of producing adequate H2O2 and altered tumor infiltrated immune cell species, driven by effective lactate consumption with AaLS/LOX/CAT, could efficiently suppress CT26 tumor growth in vivo." (PMID 36597089, 2023). "We did not observe a significant difference in tumor growth or survival between catalase-treated and untreated mice when either approach was used." (PMID 37311396, 2023). "Although the intracellular catalase approach does not achieve the same level of additional catalase activity in the tumor as with extracellular catalase, it does elevate catalase activity throughout the tumor." (PMID 37311396, 2023). "While the local administration of AaLS/LOX to the tumor site resulted in mice death, that of AaLS/LOX/CAT significantly suppressed tumor growth without any severe side effects." (PMID 36597089, 2023).
tumor (continued). "EC mice exposed to combined treatment of CuNPs and radiation showed a marked reduction in tumor volume, ALT and CAT, creatinine, calcium, and GSH, along with elevation in MDA, caspase-3 in parallel with inhibition of NF-κB, p38 MAPK, and cyclin D1 gene expression." (PMID 36905557, 2023). "Tumor growth and survival demonstrated that neither the expression of intracellular catalase nor a combination of intra- and extracellular catalase had observable efficacy in either tumor model." (PMID 37311396, 2023). "Despite prolonged tumor-localized catalase activity, catalase alone or in combination with radiation did not improve treatment efficacy, as measured by primary tumor growth and survival, contrasting with prior studies." (PMID 37311396, 2023). "On the other hand, by taking advantage of excessive amounts of H2O2 within the TME, the CAT could induce the decomposition of tumor endogenous H2O2 and generate O2 in situ, alleviating tumor hypoxia." (PMID 37765212, 2023). "It presented a stronger ability to generate cytotoxic reactive oxygen species and consequently destroy tumor cells upon light irradiation, in comparison with its counterpart without catalase or perfluoropolyether." (PMID 36900370, 2023). "Despite observing long-lived catalase presence and activity at the tumor, neither extracellular or intracellular catalases altered tumor growth or gene expression associated with hypoxia or oxidative stress." (PMID 37311396, 2023). "CpG islands hypermethylation has also been observed in tumor tissues, along with decreased levels of CAT mRNA and protein expression when compared to non-tumor tissues." (PMID 37176094, 2023). "According to the GO results, catalase (CAT), peroxiredoxin-1 (PRDX1), and PRDX4 were related to hydrogen peroxide catabolic process and reactive oxygen species metabolic process, which led to tumor cell apoptosis." (PMID 37124724, 2023). "In tumor tissues, the ZnO2@PEG NPs would rapidly release Zn ion and H2O2 due to mild acidity and low catalase activity, subsequently triggering the enhanced Fenton/Fenton‐like reactions with the intrinsic Fe, utilizing hydroxyl radical and burst increased Zn ion for efficient therapy." (PMID 35712774, 2022). "At the same time, the combined work of CAT and MnO2 could effectively consume H2O2 and GSH to reoxygenate the hypoxic tumor via catalyzing endogenous hydrogen peroxide to O2, and 1O2, respectively; meanwhile generated Mn2+ serves as a contrast agent." (PMID 36531004, 2022). "Importantly, PTT was found to significantly boost the nanozyme efficacy of both catalase (CAT) and peroxidase (POD) processes, which correspondingly decompose H2O2 to into O2 to relieve tumor hypoxia, and activate H2O2 to generate oxidative •OH radical." (PMID 36153526, 2022). "Excessive levels of ROS can be controlled in both the tumor and physiological environment using antioxidant enzymes, such as superoxide dismutase (SOD), catalase (CAT), glutathione (GSH), and peroxiredoxins (Prxs), as well as nonenzymatic antioxidants, such as vitamins E and A." (PMID 35524662, 2022). "However, studies showed that the interactions of singlet oxygen produced by CAP triggered tumor cell production of higher concentrations of secondary singlet oxygen, resulting in the profound inactivation of protective catalase and SOD in tumor cells." (PMID 35646968, 2022). "Using catalase addition as a solution to ICS artifact was also found to be effective for intratumoral T cell analysis in crude tumor samples, a widely employed measurement to evaluate immunosuppression within the tumor microenvironment." (PMID 35126389, 2022). "The immediate vicinity of tumor cells (tumor microenvironment, or TME) is mildly acidic and accompanied by the overproduction of H2O2, low oxygenation (hypoxia), and reduced activity of certain enzymes such as CAT." (PMID 35740402, 2022).
tumor (continued). "On the other hand, Ingenuity pathway analysis software (IPA, Qiagen) identified three genes with notably decreased mRNA levels upon chemerin treatment, USP12, CAT and PTK2 (FAK), which exert tumor-promoting effects and stimulate proliferation of cancer cell lines in vitro." (PMID 36077645, 2022). "The CAT catalyzes the endogenous H2O2 into O2 to relieve the hypoxic microenvironment, and the released HA-HMME exhibits a higher ROS generation ability, greatly boosting SDT for the inhibition of tumor growth." (PMID 35387175, 2022). "The H2O2 produced in the blood stream by circulating MWCNTs-DAAO does not induce significant side effects since a 50-fold higher catalase activity in blood compared to tumor tissues was reported." (PMID 35467257, 2022). "Like CAT, the nanozymes could trigger the degradation of H2O2 into O2 to meliorate the tumor hypoxia, which is beneficial for PDT." (PMID 35384520, 2022). "In fact, the tumor micro-environment often displays high levels of H2O2, which can be converted to O2 by catalase enzymes or inorganic systems mimicking enzyme activity, as observed for catalase associated to iron oxide nanoparticles that produced O2 bubbles in tumors under HIFU application." (PMID 35300712, 2022). "Owing to the catalase and smallest size, SPNC1 could not only penetrate throughout the tumor interstitium but also react with H2O2 overproduced in the TME to generate O2." (PMID 34989170, 2022). "Another immunoliposome was developed, known as CAT@aPDL1-SSL, which represents another immunoliposome developed that contains catalase (CAT)-encapsulated liposomes and a modified PDL-1 for improving immunotherapeutic effects, enhancing T cells in tumor tissues, and blocking the PD-1/PD-L1 pathway." (PMID 35214129, 2022). "Recently, genetically modified Escherichia coli (E. coli) with overexpressed human catalase was combined with photosensitizers such as chlorin e6 and black phosphorus quantum dots, and enhanced PDT by catalyzing H2O2 into O2 in the tumor site." (PMID 35053229, 2022). "Nevertheless, the level of H2O2 in tumor cells does not have sufficient capacity to support abundant O2 production even catalase presents favorable catalytic performance." (PMID 34791801, 2022). "Furthermore, to ameliorate tumor hypoxia and enhance PDT, two nanometals made up of Au and rhodium (Rh) (Au@Rh) with catalase activities were developed as nanoenzyme." (PMID 36230480, 2022). "(V) As a result, CAT@HA-HMME NPs can activate more 1O2-triggered irreversible oxidation of cancer cells through double enhancement, resulting in the internal physiological and metabolic dysfunction and inhibition of tumor growth." (PMID 35387175, 2022). "Luteolin alone induced an increase in superoxide dismutase (SOD), catalase (CAT) and glutathione peroxidase (GPx) in non-tumoral tissues and serum, as well as a decrease in tumor." (PMID 35056792, 2022). "However, due to the intrinsic hypoxic environment in the tumor, OXD-mimicking nanozymes are usually in combination with CAT or CAT mimics that can provide sufficient O2 for cascade catalytic therapy." (PMID 35384520, 2022). "In more detail, CAT and DOX loaded in the ZIF-8 was used as the core to generate oxygen and reserve chemodrug, while the murine melanoma cell membrane was used as the shell to provide tumor targeting ability and elicited immune response." (PMID 34277702, 2021). "Moreover, animals bearing tumor treated with both AT and Gl revealed high elevation in tumor Malondialdehyde (MDA) accompanied by a detectable decline in GSH, SOD and CAT activities in comparison to the Ehrlich group than in each treatment alone." (PMID 33906301, 2021). "As a control experiment, LOx alone (FIGs-L) without CAT killed both the normal and tumor cells because of the produced H2O2." (PMID 34475406, 2021).
tumor (continued). "Tumor cells protect themselves by activating an antioxidant system that involves glutathione (GT), glutathione peroxidase (GPx), glutathione S-transferase (GST), glutaredoxin (Grx), thioredoxin (Trx), superoxide dismutase (SOD), and catalase (CAT)." (PMID 34885879, 2021). "It is also obvious that the hierarchy of interactions established for MKN-45 cells is specifically relevant for tumor cells and has no impact on nonmalignant cells, as these lack the key features of active NOX1 and membrane-associated catalase." (PMID 34679719, 2021). "None of the long-lived species found in PAM, such as nitrite and H2O2, nor OCl− or NO seem to have the potential to interfere with catalase-dependent control of apoptotic cell death-inducing signalling within tumour cells when acting alone." (PMID 33801451, 2021). "Since the normal tissue architecture of parotid glands is lost during neoplastic transformation, we were only able to observe an apparently higher expression of catalase in tumor tissue without reference to a specific glandular structure." (PMID 34360635, 2021). "Although catalase and the nanozymes are capable of catalyzing H2O2 to generate oxygen effectively, the endogenous H2O2 levels in the tumor microenvironments limit hydrogen peroxide decomposition strategies, especially in tumors with relative lower endogenous H2O2 levels." (PMID 33535466, 2021). "In addition, catalase in this composite was able to catalyze H2O2, which was generated by tumor metabolism, to produce O2." (PMID 35011360, 2021). "Investigation supports that low level 1O2 (derived from CAP or via interaction with long lived species of PAM) may interact with tumor cells surface carrying NOX1, SOD, and CAT." (PMID 33477494, 2021). "Moreover, the tumor mRNA expression of glutathione S-reductase (GSR) and superoxide dismutase 1 (SOD1) showed a trend of increase, whereas catalase (CAT) was significantly downregulated." (PMID 33668151, 2021). "Contributing to the photosensitive characteristics of Ce6 and the dual CAT- and POD-like activities simultaneously of Au2Pt nanozymes, this nanosystem not only can relieve tumor hypoxia with O2 generation but also enhance the efficiency of PDT and chemotherapy with the produced ∙OH." (PMID 34737942, 2021). "The most recent theory states that tumor progression requires the expression of membrane-bound catalase, and 1O2 (a type of short-lived species in CAP) can inactivate membrane-bound catalase and trigger the generation of tumor cell-derived secondary 1O2 and ROS-dependent apoptosis." (PMID 34476012, 2021). "As shown by 2D photoacoustic imaging for oxygenated hemoglobin (λ = 850 nm), after the intratumoral injection of the zeolite-catalase-MB (ZCM) nanocapsule, the blood oxyhemoglobin level in tumor tissues increased over time and reached its maximum after 3-h post-injection." (PMID 34138222, 2021). "CAT@liposome could degrade the sustained release of H2O2 and can achieve the lasting effect of enhancing tumor oxygenation." (PMID 33343807, 2020). "Using the ex vivo neutrophil-tumor cell co-culture, we observed reductions in neutrophil tumoricidal activity in response to either inhibition of NADPH oxidase by apocynin or HDC, or stimulation of H2O2 degradation of by catalase." (PMID 32873795, 2020). "The current study revealed a significant elevation in MDA level and ROS generation in the tumor tissues (P < 0.001) as well as a marked reduction in GSH content, CAT, and SOD enzyme activity in all treated groups compared to the nontreated SEC group tissues as shown in." (PMID 32566073, 2020). "Catalase is a specific catalytic enzyme with an extremely high turnover to decompose H2O2 into O2 and has been explored in combination with other therapeutic approaches to construct several types of nanoplatforms to relieve tumor hypoxia 155-158." (PMID 32641993, 2020).
tumor (continued). "Oxidative stress, resulting from an imbalance between ROS production and elimination by enzymatic/non-enzymatic antioxidants including superoxide dismutase (SOD), catalase (CAT), glutathione peroxidase (GPx), and glutathione (GSH), promotes tumor cell proliferation, angiogenesis, and metastasis." (PMID 32823876, 2020). "Bauer and Graves16 and Bauer17,18 suggested that low concentrations of 1O2 from CAP, or derived through interaction of long-lived species in PAM, would interact with the surface of tumor cells, that carries NOX1, catalase and SOD, in the same way for extracellular 1O2 generated by a photosensitizer." (PMID 31578342, 2019). "The activities of SOD and CAT were significantly higher in the adjacent noncancerous tissues than those in tumor tissues, while the activities of GSH-related enzymes were significantly higher in tumor tissues than in the adjacent noncancerous tissues." (PMID 31781331, 2019). "Treatment of MKN 45 tumor cells with CAP for 1 min, followed by 25 minutes incubation and a washing step, allowed subsequent apoptosis induction to a similar degree as the direct inhibition of catalase by 3-AT." (PMID 31578342, 2019). "The expression of antioxidant-related enzymes, such as MnSOD, in stage III and IV CRC tumor samples was shown to be increased, and the expression of several antioxidant enzymes, including catalase and GPx, was also increased in adjacent nontumor tissues." (PMID 30781816, 2019). "The finding of an overall low concentration of catalase in tumor cells is, however, not at all in contradiction to the strong expression of catalase on the membrane of tumor cells." (PMID 31578342, 2019). "It is important to recall that successful imprinting is absolutely dependent on the covalent attachment of the catalase molecules to the surface of the tumor cells, which allows the establishment of a site of protection of H2O2 and ONOO− after inactivation of few catalase molecules." (PMID 31558835, 2019). "Treatment of tumor cells with CAP for one minute without the subsequent incubation period was not sufficient for the inactivation of catalase." (PMID 31578342, 2019). "On the other hand, treatment of the Ehrlich solid tumor group with Avns revealed a significant (P < 0.05) increase in the levels of CAT, GSH, and SOD and a significant (P < 0.05) decrease in the level of MDA in tumor tissue as compared with the Ehrlich solid tumor group." (PMID 30755785, 2019). "Thus the role of primary 1O2 generated from long-lived species derived from CAP treatment seems to be restricted to a merely triggering function for the “biochemical switchboard” of the tumor cells that is composed of NOX1, catalase and SOD." (PMID 31578342, 2019). "In other respects, the OS parameters: NO (Nitrogen monoxide), AOPP (Advanced Oxidation Protein Products) and MDA (Malondialdehyde) were higher in tumor tissues compared to peritumoral stroma (control), unlike the catalase activity." (PMID 30364567, 2018). "Ultimately, catalase-loaded Pt (IV)-liposomes synergised with radiation to control subcutaneous tumour growth in mice, though alone, these liposomes failed to inhibit tumour growth despite including the cisplatin prodrug." (PMID 30261606, 2018). "Reduced CAT activity has been reported in cancer and suppression of CAT increases H2O2 levels, which in turn stimulates H2O2-dependent signaling pathways that promote tumor progression." (PMID 30260967, 2018).